LINC02210 (long intergenic non-protein coding RNA 2210 )
Gene: Transcribed unitary pseudogene on chromosome 17 (45,633,049 to 45,636,444, forward strand). Ensembl gene ENSG00000204650.
Diseases named in the same sentence as LINC02210 in open-access papers:
LINC02210 is named in the same sentence as 4 diseases in open-access papers, as found by Europe PMC text mining. Sharing a sentence is not in itself a finding about the gene and the disease. The quoted sentences say what the papers report.
schizophrenia (2 papers, 2021 to 2025). A major psychotic disorder characterized by abnormalities in the perception or expression of reality. "Within the fetal analysis, genes located in chr17q21.31, such as MAPT-AS1, KANSL1, LINC02210, MAPK8P1P2, and RP11-259G18.1, were regulated by eQTLs that have known associations with cognition, schizophrenia, and alcohol consumption traits." (PMID 40000109, 2025).
autism (1 paper, 2023). Persistent deficits in social interaction and communication and interaction as well as a markedly restricted repertoire of activity and interest as well as repetitive patterns of behavior. "However, neither LINC02210 nor RP11−259G18.1 have previously been identified as causal autism genes." (PMID 37553252, 2023).
Parkinson disease (1 paper, 2025). A progressive degenerative disorder of the central nervous system characterized by loss of dopamine producing neurons in the substantia nigra and the presence of Lewy bodies in the substantia nigra and locus coeruleus. "Within the adult cortical analysis, KANSL1 and LINC02210 (chr17q21.31 cluster identified in the fetal analysis) were associated with eQTLs that were associated with brain-related traits (e.g., mood traits and Parkinson’s disease)." (PMID 40000109, 2025).
LINC02210 also shares sentences with these, for which no sentence is quoted: behavioral disorders (1 paper).